SNORD45B (small nucleolar RNA, C/D box 45B)
Synonyms: U45b; RNU45B
Gene: Small nucleolar RNA gene on chromosome 1 (75,789,477 to 75,789,548, forward strand). Ensembl gene ENSG00000201487.
Gene Ontology:
Biological process: RNA processing
Cellular component: nucleolus
Homologues: Orthologues: chimpanzee SNORD45B (100% identical), macaque SNORD45B (99% identical), rabbit SNORD45B (90% identical), guinea pig SNORD45B (89% identical), mouse Snord45b (83% identical), rat Snord45b (81% identical). Paralogues in human: SNORD45A (86% identical), SNORD45C (85% identical).